DLG5 (discs large MAGUK scaffold protein 5)
Diseases named in the same sentence as DLG5 in open-access papers (continued):
Sharing a sentence is not in itself a finding about the gene and the disease.
inflammatory bowel disease (3 papers, 2014 to 2018). A spectrum of small and large bowel inflammatory diseases of unknown etiology. "DLG5 can form a variety of complexes with other proteins and plays an important role in regulating cell growth, cell migration, maintaining the structural integrity of the epithelial cells, and signal transmission; DLG5 is associated with inflammatory bowel disease." (PMID 29363554, 2018). "Growing evidence from recent studies has demonstrated an association between inflammatory bowel disease (IBD) susceptibility and two polymorphisms of DLG5 R30Q (rs1248696) and P1371Q (rs2289310), but the results remain controversial." (PMID 27633114, 2016). "DLG5 function is lost in the KAD rat; this protein is also defective in inflammatory bowel disease (IBD), suggesting an association between APC and IBD." (PMID 25288683, 2014).
prostate carcinoma (3 papers, 2012 to 2021). A carcinoma that arises from epithelial cells of the prostate gland. "To investigate whether Dlg5 function in the regulation of EMT is cell-type specific, we used PC3 cells, which are derived from human prostate cancer." (PMID 22539977, 2012).
glioblastoma (2 papers, 2020 to 2024). The most malignant astrocytic tumor (WHO grade IV). "Our findings first revealed that PABPC1/BDNF-AS/RAX2/DLG5 module plays an important role in glioblastoma cells, provided insight into potential therapeutic targets to treat glioma." (PMID 32015336, 2020). "Knockdown of RAX2 produced tumor-suppressive function in glioblastoma cells and increased the expression of discs large homolog 5 (DLG5), leading to the activation of the Hippo pathway." (PMID 32015336, 2020). "Knockdown of RAX2 increased DLG5 expression thereby inhibited the malignant biological behaviors of glioblastoma cells by activating the Hippo pathway." (PMID 32015336, 2020). "Overexpression of DLG5 inhibited glioblastoma tumor malignancy by activating the Hippo signaling pathway." (PMID 32015336, 2020). "Overexpression of PABPC1, BDNF-AS, and DLG5 along with depletion of RAX2 inhibited malignant biological behaviors of glioblastoma cells." (PMID 32015336, 2020). "We demonstrated for the first time that the PABPC1/BDNF-AS/RAX2/DLG5 pathway plays the vital role in regulating the malignant biological behaviors of glioblastoma cells." (PMID 32015336, 2020). "The results indicated that DLG5 is involved in RAX2 regulation in glioblastoma cells." (PMID 32015336, 2020). "Overexpression of DLG5 inhibited glioma cells malignant biological behaviors of glioblastoma cells." (PMID 32015336, 2020). "However, two independent studies on glioblastoma reported conflicting effects of DLG5 on tumors." (PMID 39605072, 2024). "We proposed that DLG5 may exert tumor-suppressive function in glioblastoma cells." (PMID 32015336, 2020). "In this study, we first showed that overexpression of DLG5 activated the Hippo pathway by increasing the phosphorylation of YAP and suppressed the malignant behaviors of glioblastoma cells consequently." (PMID 32015336, 2020).
pancreatic cancer (2 papers, 2012 to 2025). "In another study, KIF20A colocalized with discs large MAGUK scaffold protein 5 (DLG5) in pancreatic cancer, a protein known to interact with cell cycle regulators and implicated in tumorigenesis." (PMID 41392981, 2025). "Reduction of Dlg5 expression significantly inhibited the proliferation of pancreatic cancer cell lines." (PMID 22539977, 2012). "Interestingly, expression of Dlg5 in pancreatic cancers correlates with metastasis to the lymph nodes." (PMID 22539977, 2012).
pituitary tumor (2 papers, 2022 to 2023). A benign or malignant neoplasm affecting the pituitary gland. "DLG5 was recently identified to be a novel tumor related gene in pituitary tumors as based on single cell data, and has also been shown to be associated with overall survival in HCC." (PMID 36408192, 2022).
astrocytoma (1 paper, 2021).
celiac disease (1 paper, 2013). An autoimmune genetic disorder with an unknown pattern of inheritance that primarily affects the digestive tract. "Similar to MYOIXB, PARD3, and MAGI2 variants, the DLG5 R30Q polymorphism has also been reported to be associated with celiac disease, corroborating the concept that a common mechanism, that is breakdown of the intestinal barrier, may exist between celiac disease and IBD." (PMID 24062746, 2013).
cyst (1 paper, 2011). A sac-like closed membranous structure that may be empty or contain fluid or amorphous material. "For example, mutations in mouse Dlg5 perturb delivery of adherens complex proteins to the plasma membrane of brain and kidney epithelial tubes, resulting in cyst formation." (PMID 21750678, 2011).
Dyspareunia (1 paper, 2022). Recurrent or persistent genital pain associated with sexual intercourse. "We identified a DLG5 variant in patient Fc-M-6 who was diagnosed as having type I MRKH syndrome (ESHRE classification: U5bC4V4) with primary amenorrhea and dyspareunia." (PMID 35361250, 2022).
E. coli infection (1 paper, 2018). "The results suggested that miR-192 and its key target genes (DLG5 and ALCAM) could have a key role in E. coli infection." (PMID 29363554, 2018). "The results suggested that miR-192 and its key target genes (DLG5 and ALCAM) could have a key role in E. coli infection in piglets." (PMID 29363554, 2018).
glioma (1 paper, 2020). A benign or malignant brain and spinal cord tumor that arises from glial cells (astrocytes, oligodendrocytes, ependymal cells). "In summary, we first found that PABPC1, BDNF-AS, and DLG5 were downregulated in human glioma tumors and cells, while RAX2 was upregulated conversely." (PMID 32015336, 2020). "In our study, we provided the endogenous expression and functions of PABPC1, BDNF-AS, RAX2, and DLG5 in human glioma tumor specimens and cells." (PMID 32015336, 2020). "Our results proved that DLG5 had a low expression level in glioma tissues and cells." (PMID 32015336, 2020).
head and neck squamous cell carcinoma (1 paper, 2024). A squamous cell carcinoma that arises from any of the following anatomic sites: lip and oral cavity, nasal cavity, paranasal sinuses, pharynx, larynx, and salivary glands. "Sangerbox online tool analysis demonstrated that DLG5 was highly expressed in head and neck squamous cell carcinoma (HNSCC) based on RNA-seq data from The Cancer Genome Atlas (TCGA)." (PMID 39605072, 2024).
influenza infection (1 paper, 2013). "Correspondingly, we also observed an increase in DLG5 expression upon influenza infection and we show that DLG5 could be regulated by miR-628-3p." (PMID 24116168, 2013).
oral squamous cell carcinoma (1 paper, 2024). "In conclusion, our study revealed that lactate derived from cancer-associated fibroblasts promotes the CSCs phenotype in oral squamous cell carcinoma through the DLG5/CUL3/MST1 signaling axis." (PMID 39605072, 2024). "Additionally, the knockdown of DLG5 inhibited the CSCs phenotype in oral squamous cell carcinoma." (PMID 39605072, 2024).
ovarian carcinoma (1 paper, 2020). A malignant neoplasm originating from the surface ovarian epithelium. "β-Trcp regulates the Discs large homolog 5 (Dlg5) that inhibit HCC cell proliferation, and AE Binding Protein 2 (AEBP2) that induces ovarian cancer cells proliferation and cisplatin resistance." (PMID 32486158, 2020).
renal agenesis (1 paper, 2022). Renal agenesis (RA) is a form of renal tract malformation characterized by the complete absence of development of one or both kidneys (unilateral RA or bilateral RA respectively), accompanied by absent ureter(s). "Heterozygous sequence variants of DLG5 are associated with ureteropelvic junction obstruction or renal agenesis." (PMID 35361250, 2022).
renal fibrosis (1 paper, 2012). A final common manifestation of a wide variety of chronic kidney diseases characterized by glomerulosclerosis and tubulointerstitial fibrosis. "It is of interest that cysts found in the kidneys of Dlg5 knockout mice have a fibrous surface, because fibroblasts derived from tubular epithelial cells via EMT are a major source for the secretion and deposition of excess extracellular matrix in renal fibrosis." (PMID 22539977, 2012).
tumor (19 papers, 2014 to 2025). "Given the critical role of Dlg5 to maintain cell polarity, cells stably expressing Dlg5 S730A mutations will continue to maintain cell polarity and inhibit tumor development." (PMID 31787846, 2019). "DLG5 is associated with GBM stem cell invasion with under expression (demonstrated through knock down experiment) previously shown to cause disruption of GBM tumor formation and been associated with increased patient survival." (PMID 39766155, 2024). "It has been shown that the methylation of the promoter region of DLG5 may be associated with its low expression in some tumor tissues." (PMID 31787846, 2019). "Taken together, loss of DLG5 promotes tumor malignancy by regulating cell overgrowth." (PMID 28169360, 2017). "Further analysis of tumor tissue samples revealed a positive correlation between DLG5 expression and both histopathological grade and clinical stage, independent of age, gender, or recurrence." (PMID 39605072, 2024). "Acting as a ceRNA platform, LINC00589 acts as a sponge for miR-100 and miR-452, thus relieving their suppression of tumor suppressors such as DLG5 and PRDM16." (PMID 37781073, 2023). "In HER2+ breast cancer 24, LINC00589 overexpression significantly decreased tumor volume and weight, inhibited luciferase activity, and upregulated DLG5 and PRDM16 protein expressions." (PMID 37781073, 2023). "Overexpression of DLG5 was found to be tumor-promoting contrary to the cancer literature on this gene." (PMID 31277598, 2019). "As expected, SMMC-7721 cells stable expressing of a non-degradable Dlg5 S730A mutant dramatically decreased tumorigenesis, as the tumor volume was significantly decreased compared with Dlg5 WT group." (PMID 31787846, 2019). "Consistent with these in vitro data, we also found that cells stably expressing Dlg5 S730A significantly inhibited tumor growth in nude mice than Dlg5 WT." (PMID 31787846, 2019). "Knockdown of DLG5 increased tumor weight and volume and elicited a remarkable increase in YAP and a decrease in Scribble." (PMID 28169360, 2017). "DLG5, a scaffold protein essential for epithelial integrity, may be suppressed in tumor tissues but upregulated in circulation through inflammation-induced signaling pathways such as NF-κB and MAPK activation." (PMID 41373777, 2025). "This article also defined AMIGO2, ZFP36, BTG1, and DLG5 tumor-related genes." (PMID 39114291, 2024). "Considering the high glycolytic activity of CAFs, which results in an acidic tumor microenvironment, we investigated whether this could lead to increased expression of DLG5 in tumor tissues." (PMID 39605072, 2024). "The effect of Dlg5 on HCC tumor growth in vivo was studied in a tumor xenograft model in mice." (PMID 31787846, 2019). "Down-regulation of DLG5 is highly correlated with clinical tumor stage." (PMID 28169360, 2017). "Interestingly, evidence is emerging to lend support to our finding that DLG5 might be tumor-promoting." (PMID 31277598, 2019). "Further investigation revealed that lactate derived from CAFs negatively regulates the HIPPO pathway through the DLG5/CUL3/MST1 axis, thus promoting the nuclear localization of YAP1 and enhancing the tumor stem cell phenotype." (PMID 39605072, 2024). "This research led to the discovery of several new tumor-related genes, including AMIGO2, ZFP36, BTG1, and DLG5." (PMID 38275385, 2023). "The single-cell transcriptome and single-cell multi-omics analyses revealed that novel tumor-related genes, such as AMIGO2, ZFP36, BTG1, and DLG5, were mainly upregulated in pituitary neuroendocrine tumors." (PMID 38098508, 2023). "Novel tumor-related genes like AMIGO2, ZFP36, BTG1, and DLG5 have been identified." (PMID 38275385, 2023). "Persistent dlg1 germ line clones develop into eggs, whereas follicle cells lacking dlg1 sometimes show tumor-like invasion into the interior of the egg chamber, a phenotype we did not observe in Dlg5 KD." (PMID 25795662, 2015).
tumor (continued). "Moreover, scRNA-seq results identified novel tumor suppressor genes (ZFP36, BTG1, DLG5, and ZBTB16), cell apoptosis-inhibitor genes, genes with pro-tumoral functionality (C1Q in TAMs), and many cell cluster-specific genes, including tumor and stromal cell-specific marker genes." (PMID 39114291, 2024). "To further demonstrate the effect of CAFs-derived lactate on tumor cells, we knocked down Monocarboxylate transporter 4 (MCT4), a key mediator of lactate transport across the plasma membrane, in CAFs and co-cultured them with tumor cells, with or without DLG5 knockdown." (PMID 39605072, 2024). "Moreover, IHC assay data in xenograft tumor tissues revealed that LINC00589 overexpression could upregulate the protein expressions of DLG5 and PRDM16, while miR-100 and miR-452 abrogated the promotion of LINC00589 on the DLG5 and PRDM16, respectively." (PMID 36309503, 2022).
cancer (8 papers, 2008 to 2024). A tumor composed of atypical neoplastic, often pleomorphic cells that invade other tissues. "In addition, loss of DLG5 promoted cancer malignancy by inactivating the Hippo pathway in breast cancer." (PMID 32015336, 2020). "According to several publicly available data sets, DLG5 is also associated with cancer development." (PMID 28169360, 2017). "Low expression of DLG5 has been positively correlated with the development and progression of several cancers, including lung squamous cell carcinoma, breast cancer, liver cancer, prostate cancer, and bladder cancer." (PMID 39605072, 2024). "Collectively, these results indicate that LINC00589 regulates trastuzumab resistance, cancer stem cell-like properties and multiple chemoresistance, at least in part, by modulating DLG5 and PRDM16 expression." (PMID 36309503, 2022). "DLG5 belongs to the membrane associated guanylate kinase (MAGUK) family, participates in epithelial cell polarity maintenance and cancer development." (PMID 32015336, 2020). "The role of human DLG5 in cancer proliferation, migration, and cancer development has been reported." (PMID 31856229, 2019). "In this work, we showed that Drosophila Dlg5 promotes collective cell migration by regulating the cluster polarity, providing clues to DLG5’s roles in cancer metastasis." (PMID 31856229, 2019). "DLG5 is highly expressed in normal tissues, but its expression is decreased or lost in cancer cell lines." (PMID 28169360, 2017). "Discs large homolog 5 (Dlg5) is a member of the membrane-associated guanylate kinase (MAGUK) adaptor family of proteins and its deregulation has been implicated in the malignancy of several cancer types." (PMID 31787846, 2019). "Low-grade cancer tissues had higher expression of DLG5 than high-grade cancer tissues." (PMID 28169360, 2017). "Furthermore, we used shRNA to knock down DLG5 expression in cancer cells." (PMID 39605072, 2024). "DLG5 possesses four PDZ domains, one SH3 domain, and one GUK domain, which play crucial roles in the maintenance of epithelial cell polarity and cancer progression." (PMID 39605072, 2024). "DLG5 belongs to the MAGUK family, participates in epithelial cell polarity maintenance and cancer development." (PMID 32015336, 2020). "It has been recently found that lower DLG5 expression is correlated with advanced stages of HCC and essential for invadopodium formation, an event critical to cancer metastasis." (PMID 31277598, 2019).
DLG5 also shares sentences with these, for which no sentence is quoted: asthma (1 paper); chronic lymphatic leukaemia (1); congenital heart disease (1); diabetes (1); familial hypercholesterolemia (1); gallstones (1); Hydrolethalus (1); infection (1); Kidney Cyst (1); liver disease (1); male infertility (1); Myokymia (1); nephrotic syndrome (1); Obesity (1); obstructive hydrocephalus (1); pituitary adenomas (1); Primary amenorrhea (1); primary ciliary dyskinesia (1); respiratory diseases (1); ulcerative colitis (1).